RAPGEF3 (Rap guanine nucleotide exchange factor 3)
Description:
Guanine nucleotide exchange factor (GEF) for RAP1A and RAP2A small GTPases that is activated by binding cAMP. Through simultaneous binding of PDE3B to RAPGEF3 and PIK3R6 is assembled in a signaling complex in which it activates the PI3K gamma complex and which is involved in angiogenesis. Plays a role in the modulation of the cAMP-induced dynamic control of endothelial barrier function through a pathway that is independent on Rho-mediated signaling. Required for the actin rearrangement at cell-cell junctions, such as stress fibers and junctional actin.
Synonyms: cAMP-GEFI; EPAC; EPAC1; bcm910; HSU79275
Tractability: Small molecule: a structure with a bound ligand is known; a high-quality ligand is known. Antibody: its Gene Ontology location is reachable by antibodies, with high confidence. PROTAC: a small molecule that binds it is known.
Gene: Protein-coding gene on chromosome 12 (47,734,363 to 47,771,040, reverse strand). Ensembl gene ENSG00000079337.
Subcellular location: Endomembrane system
Subcellular location (Human Protein Atlas): Cytosol; Endoplasmic reticulum
Pathways (Reactome):
Metabolism: Glucagon-like Peptide-1 (GLP1) regulates insulin secretion; Regulation of insulin secretion
Immune System: Rap1 signalling
Signal Transduction: Integrin signaling
Gene Ontology:
Molecular function: guanyl-nucleotide exchange factor activity; protein binding; protein domain specific binding; cAMP binding
Biological process: cellular response to cAMP; establishment of endothelial barrier; intracellular signal transduction; negative regulation of syncytium formation by plasma membrane fusion; positive regulation of angiogenesis; positive regulation of GTPase activity; positive regulation of protein export from nucleus; positive regulation of stress fiber assembly; positive regulation of syncytium formation by plasma membrane fusion; Rap protein signal transduction; regulation of actin cytoskeleton organization; regulation of angiogenesis; regulation of phosphatidylinositol 3-kinase/protein kinase B signal transduction; adaptive immune response; adenylate cyclase-activating G protein-coupled receptor signaling pathway; positive regulation of insulin secretion; signal transduction; associative learning; small GTPase-mediated signal transduction
Cellular component: cortical actin cytoskeleton; endoplasmic reticulum; extracellular exosome; filopodium; lamellipodium; microvillus; plasma membrane; membrane; endomembrane system
Genetic constraint (gnomAD): Loss-of-function variants: 103 observed, 127.15 expected, observed/expected ratio (o/e) 0.81, 90% interval 0.69 to 0.95. The upper end of that interval is the gene's LOEUF score, 0.95, which puts it in group 4 of 6, group 1 being the genes least tolerant of losing a copy. Missense variants: 1,117 observed, 1,192 expected, observed/expected ratio (o/e) 0.94, 90% interval 0.89 to 0.99. Synonymous variants: 436 observed, 478.82 expected, observed/expected ratio (o/e) 0.91, 90% interval 0.84 to 0.99.
Homologues: Orthologues: chimpanzee RAPGEF3 (99% identical), macaque RAPGEF3 (98% identical), dog RAPGEF3 (94% identical), pig RAPGEF3 (94% identical), guinea pig RAPGEF3 (93% identical), mouse Rapgef3 (91% identical), rat Rapgef3 (90% identical), tropical clawed frog rapgef3 (57% identical), zebrafish rapgef3 (52% identical). Paralogues in human: RAPGEF4 (47% identical), RAPGEF5 (31% identical), RAPGEFL1 (22% identical), RAPGEF2 (20% identical), RAPGEF6 (19% identical), RAPGEF1 (16% identical), RASGRF1 (14% identical), RASGRF2 (14% identical), SOS1 (13% identical), SOS2 (13% identical), RALGDS (12% identical), RASGEF1B (12% identical), and 12 more.
Diseases named in the same sentence as RAPGEF3 in open-access papers:
RAPGEF3 is named in the same sentence as 107 diseases in open-access papers, as found by Europe PMC text mining. Sharing a sentence is not in itself a finding about the gene and the disease. The quoted sentences say what the papers report.
diabetes (13 papers, 2015 to 2026). "Of the new loci identified, EPAC1 (RAPGEF3) is known to play a role in energy homeostasis, diabetes and obesity propensity and regulates insulin and leptin signalling." (PMID 30121879, 2018).
atherosclerosis (9 papers, 2015 to 2026). A disease characterized by the build-up of fatty material and calcium deposition in the arterial wall resulting in partial or complete occlusion of the arterial lumen. "In addition, GSTA4, RAPGEF3, TRPV4, INSIG1, UTS2, and PPP1R1A all play a role in the development of atherosclerosis." (PMID 39758846, 2024).
breast carcinoma (7 papers, 2019 to 2024). "We identified 7 genes (ITGB1, SNAI1, NOTCH4, STAT5B, RAPGEF3, LAMA2, and GNAI1) that have been implicated in both stemness and the drug response and validated their relevance through an analysis of data from breast cancer patients in the TCGA database using UCSC Xena." (PMID 39180549, 2024).
lung carcinoma (7 papers, 2019 to 2025). "Our current study supports the notion that targeting RAPGEF3 could serve as a promising therapeutic strategy for overcoming AST-mediated TKI resistance in EGFR-mutant lung cancer." (PMID 39687207, 2024). "For patients with TKI resistance and AST, the combination of RAPGEF3 inhibitor and TKI (such as osimertinib + ESI-09) can overcome the resistance mediated by AST, especially in lung cancers with high RAPGEF3 expression." (PMID 40568576, 2025).
asthma (4 papers, 2019 to 2025). "We also discovered the locus-locus interaction of DNAm levels of the CDH6 gene and RAPGEF3 gene might interact with each other to jointly predict the risk of asthma – which suggests the pivotal role of cell-cell junction in the pathological changes of asthma." (PMID 31932625, 2020). "Interestingly, the authors also discovered that the DNAm levels of the CDH6 gene and RAPGEF3 gene might interact with each other to jointly predict the risk of asthma, which suggests the pivotal role of cell–cell junctions in the pathological changes of asthma." (PMID 35055381, 2022). "RAPGEF3 may work synergistically with another candidate gene, cadherin-6 (CDH6), to influence asthma risk." (PMID 39858200, 2025). "In our study, we also detected changes in the expression of RAPGEF3 and related genes in asthmatic Meishan pigs, indicating that RAPGEF3 may be involved in the airway smooth muscle remodeling process in asthma." (PMID 39858200, 2025). "Future studies could investigate the interaction between RAPGEF3 and other genes in the context of asthma pathogenesis." (PMID 39858200, 2025). "The AEC data show that Rap Guanine Nucleotide Exchange Factor 3 (RAPGEF3) gene might act in concert with another candidate gene, cadherin-6 (CDH6) gene, to jointly influence the risk of asthma." (PMID 31932625, 2020).
metabolic syndrome (4 papers, 2016 to 2025). A cluster of metabolic risk factors for CARDIOVASCULAR DISEASES and TYPE 2 DIABETES MELLITUS. "Rapgef3/Epac1 knockout mice display pancreatic beta-cell dysfunction and metabolic syndrome, which are known risk factors for sensorineural hearing loss." (PMID 36656851, 2023).
Alzheimer disease (3 papers, 2016 to 2021). A progressive, neurodegenerative disease characterized by loss of function and death of nerve cells in several areas of the brain leading to loss of cognitive function such as memory and language. "Ten DEGs, including IGF1, VEGFC, RAPGEF3, PIK3CA, Akt3, ITGB3, ITGA11, SPP1, NOS1, and ATP6V0B, were selected from Rap1, oxidative phosphorylation, and Alzheimer’s disease signaling pathways." (PMID 34359260, 2021).
hearing loss (2 papers, 2023 to 2026). "We also identify four additional novel candidate genes (COL5A1, HMMR, RAPGEF3, and NNT) in which rare variant burden may be associated with hearing loss." (PMID 36656851, 2023).
Encephalopathy (1 paper, 2023). Encephalopathy is a term that means brain disease, damage, or malfunction. "For example, the mRNA expression trend of NF1, RAB14, ADCY5, and RAPGEF3 in the blood is the same as that in encephalopathy, suggesting that the purpose of assessing brain state can be achieved by detecting blood-related indicators." (PMID 36923118, 2023).
leukemia (1 paper, 2012). A malignant (clonal) hematologic disorder, involving hematopoietic stem cells and characterized by the presence of primitive or atypical myeloid or lymphoid cells in the bone marrow and the blood. "Moreover, the up-regulation of genes involved in inhibition of apoptosis (e.g. MCL1) may promote the survival of leukemia cells with accumulated DNA damage and their expansion as suggested by an up-regulation of genes involved in cell cycle progression (AHR, AHR, TUBB2A, RAPGEF3, SERTAD1, FLT1)." (PMID 22848414, 2012).
triple-negative breast carcinoma (1 paper, 2022). An invasive breast carcinoma which is negative for expression of estrogen receptor (ER), progesterone receptor (PR), and human epidermal growth factor receptor 2 (HER2). "The RAPGEF3 is also known as EPAC1, which supports metastasis-related biological processes (BPs), such as angiogenesis, cell migration, and invasion in triple negative breast cancer cell lines." (PMID 36077026, 2022).
cancer (25 papers, 2012 to 2025). A tumor composed of atypical neoplastic, often pleomorphic cells that invade other tissues. "RAPGEF3 has been implicated in cancer progression through various downstream signals, e.g. RAPGEF3 promotes cancer cell proliferation and/or suppresses apoptosis via Rap1/Akt/CREB signaling, Rap1/B-Raf/ERK and mTOR signaling or acting synergistically with PDE4 to promote the Cyclin E1-Cnx43 axis." (PMID 39687207, 2024). "Studies on LAMA2 and RAPGEF3 have identified their role in cancer progression, through the regulation of signaling pathways." (PMID 39180549, 2024). "The analysis revealed that MAPK12, RAPGEF3, and KIT exhibited the most betweenness centrality and all were related to the cancer progression." (PMID 28044124, 2016).
tumor (13 papers, 2018 to 2025). "We notice that either EGFR TKI or RAPGEF3 inhibitor alone has marginal inhibitory effect on tumor growth, whereas the antitumor effect is dramatically enhanced upon combinational therapy in RAPGEF3high tumors." (PMID 39687207, 2024). "CTF1 and RAPGEF3 were previously reported to be parts of gene signatures related to tumor microenvironment and immune system, with the first seen downregulated and methylated in BAP1 mutated samples; PALMD was found to have low expression in metastatic UM tissues, and GSTA3 in low-survival patients." (PMID 38339073, 2024).
retinopathy (4 papers, 2017 to 2021). "Oxidative stress and hypoxia cause retinopathy by induction of miR-7 that negatively regulates the RAPGEF3/EPAC-1 (rap guanine nucleotide exchange factor 3)." (PMID 31683538, 2019).
RAPGEF3 also shares sentences with these, for which no sentence is quoted: Obesity (12 papers); cardiac hypertrophy (10); heart failure (9); pancreatic cancer (8); infection (7); melanoma (7); Arrhythmia (6); cardiovascular diseases (6); chronic obstructive pulmonary disease (6); keloid (6); myocardial ischemia (6); ovarian carcinoma (6); atrial fibrillation (5); cardiac diseases (5); metabolic disease (5); prostate carcinoma (5); Ventricular arrhythmia (5); viral infections (5); depression (4); ischemia (4); myocardial infarction (4); Anxiety (3); cardiomyopathy (3); diabetic retinopathy (3); gastric cancer (3); Hyperglycemia (3); ischemic stroke (3); neuroblastoma (3); type 2 diabetes (3); acute lymphoblastic leukemia (2).
A further 63 diseases each share a sentence with RAPGEF3 in 2 papers or fewer.